NF2 (NF2, moesin-ezrin-radixin like (MERLIN) tumor suppressor)
Diseases named in the same sentence as NF2 in open-access papers (continued):
Sharing a sentence is not in itself a finding about the gene and the disease.
meningioma (continued). "Transcriptomic alterations present in recurrent versus primary 1p-22q-NF2- meningiomas were identified using RNA sequencing (RNA-seq) data in a clinically annotated cohort." (PMID 39726707, 2024). "We built a cohort of sixteen patients with confirmed 1p-22q-NF2- meningioma samples for our analysis." (PMID 39726707, 2024). "Neurofibromatosis Type II (NFII) is a genetic condition caused by loss of the NF2 gene, resulting in activation of the YAP/TAZ pathway and recurrent Schwann cell tumors, as well as meningiomas and ependymomas." (PMID 38879607, 2024). "Further frequent non-NF2 driver mutations in meningiomas include oncogenic mutations in TRAF7, KLF4, AKT1 and SMO, which are all mutually exclusive to NF2 mutations." (PMID 39273576, 2024). "Neurofibromatosis type 2 (NF2) is an autosomal dominant disorder with characteristic bilateral vestibular schwannomas, and up to 80% of NF2 patients eventually develop meningiomas." (PMID 38828669, 2024). "A follow-up study also identified YAP1::FAM118B gene fusions, the same seen in supratentorial ependymoma, in wild-type NF2 meningiomas." (PMID 40491864, 2024). "Inactivation of the NF2 gene is one of the primary chromosomal changes observed in meningioma cells." (PMID 38919490, 2024). "The current study evidenced that a subset of pure MAM (2/7, 29%), and all MAM + M harbored a hemizygous deletion of chromosome 22q (including the NF2 gene), which is the most frequent alteration in meningiomas (adult and pediatric)." (PMID 38565263, 2024). "Meningiomas, as the second most common tumor type of NF2, often include multiple lesions and develop in young patients." (PMID 38828669, 2024). "Positive expression of PD‐L1 was observed in 38.46% (5/13) of NF2 meningiomas according to IHC results and 53.85% (7/13) of NF2 meningiomas according to Western blotting." (PMID 38828669, 2024). "Molecular differences in meningiomas have different demographic characteristics, with NF2-mutant meningiomas being more common in males, while KLF4- and POLR2A-mutant meningiomas are more common in females." (PMID 39796693, 2024). "Alterations of the tumour suppressor gene NF2, located at 22q12.2, are commonly encountered in adult meningiomas; however, there is increased frequency noted within paediatric meningiomas." (PMID 39612013, 2024). "Chromosome 22q deletion is identified in approximately 50% of meningiomas, marking this as a critical early event in the onset of NF2-related meningiomas." (PMID 39066986, 2024). "A subset was associated with the genetic alterations previously reported in meningiomas (such as a KMT2C mutation and a hemizygous deletion of chromosome 22q including the NF2 gene)." (PMID 38565263, 2024). "YAP1 fusion meningiomas resemble low-grade NF2 mutant meningiomas; based on their upregulated genes and their downregulated genes, they resemble high-grade NF2 mutant meningiomas." (PMID 39202270, 2024). "We found that NF2 meningiomas with a higher degree of merlin phosphorylation also had higher PD‐L1 expression, which further verified the function of NF2 in regulating PD‐L1." (PMID 38828669, 2024). "Here, we directly compare transcriptional profiles of recurrent and primary 1p-22q-NF2- meningiomas, building on recent molecular advances in meningioma classification by focusing on this subtype enriched for recurrent tumors." (PMID 39726707, 2024). "The same mutation is seen in neurofibromatosis type 2 (NF2), also called MISME syndrome, leading to multiple hereditary schwannomas, meningiomas and epidemics." (PMID 39768979, 2024). "To evaluate differences in the transcriptome of recurrent versus primary 1p-22q-NF2- meningiomas, we performed a differential comparison using RNA-seq data." (PMID 39726707, 2024). "TIMP3 is another gene located near NF2 on chromosome 22 that has tumor suppressor-like properties in addition to inhibiting matrix metalloproteinases, and can be hypermethylated in meningiomas." (PMID 38730704, 2024).
meningioma (continued). "This work extends beyond classification and subclassification of primary meningiomas to characterize a distinct transcriptomic biomarker that is enriched in recurrent 1p-22q-NF2- meningiomas." (PMID 39726707, 2024). "The importance of deregulated YAP activity in the pathobiology of NF2 mutant meningioma is furthermore emphasized by the presence of recurrent YAP1 gene fusions (most frequently YAP1-MAML2) in around 10% of pediatric NF2 wild-type meningiomas." (PMID 38571886, 2024). "This suggests Clone #3 led to the initiation and development of the primary meningioma tumor with NF2 the main driver event." (PMID 39935847, 2024). "The expression of GSTM1 on chromosome 1p13 is downregulated in recurrent 1p-22q-NF2- meningiomas leading to a GSTM1 null genotype." (PMID 39726707, 2024). "MI meningiomas, analogous to MG2 cases (NF2-wild type), were largely benign tumors enriched for non-NF2 mutations such as TRAF7, AKT1, and KLF4." (PMID 38695575, 2024). "Subsequently, in adult zebrafish, nf2a/b knockout triggers the development of a spectrum of tumors, including vestibular schwannomas, spinal schwannomas, meningiomas, and retinal hamartomas, mirroring the tumor manifestations observed in patients with NF-2." (PMID 38712289, 2024). "In 2013, Clark and colleagues first described an association between WHO grade, histological subtype and the anatomical location of meningiomas with distinct molecular features, including mutations in TRAF7, KLF4, AKT1, SMO and NF2." (PMID 39273576, 2024). "MG1 or “immunogenic” meningiomas were defined as NF2-mutant, copy-number neutral cases enriched in immune-related transcriptomic pathways." (PMID 38695575, 2024). "The results demonstrated that GSK2256098 improved 6-month PFS in patients with recurrent or progressive NF2 mutant meningioma compared with that in the control group." (PMID 38410129, 2024). "Nf2 deletion in a wild-type background resulted in the formation of meningioma-like tumors in 19% (subdural injection, median time to tumor was 14 months) and 29% of mice (transorbital injection, median time to tumor was 11 months)." (PMID 38571886, 2024). "None the less, GSTM1 under expression is found in recurrent meningiomas from independent datasets, externally validating GSTM1- as a biomarker for 1p-22q-NF2-meningioma recurrence." (PMID 39726707, 2024). "The first group contained largely clear cell variants, the second group was predominantly atypical WHO grade 2 meningiomas in which all samples had alterations on chromosome 22 and there was the highest frequency of patients diagnosed clinically with NF2." (PMID 39612013, 2024). "While benign NF2 mutant meningiomas exhibit few genetic events in addition to NF2 inactivation, aggressive high-grade NF2 mutant meningiomas frequently harbor a highly aberrant genome." (PMID 39380691, 2024). "A phase II trial examined the effectiveness of GSK2256098 in the treatment of patients with NF2 mutant meningiomas." (PMID 38410129, 2024). "There is a higher proportion of skull base and spinal meningiomas in our study likely due to the increased proportion of NF2 patients." (PMID 39612013, 2024). "The interpretation of BRCA2 (p.E51K) as a driver mutation in this context warrants careful consideration, especially given that NF2 is a well-recognized primary driver in meningiomas." (PMID 39935847, 2024). "Higher-grade meningiomas occur in all molecular subgroups but are enriched in NF2 mutant meningiomas." (PMID 38571886, 2024). "NF2 patients can develop new meningiomas throughout their lives and often need multiple surgeries to resect these tumors." (PMID 38828669, 2024). "Most sporadic meningiomas exhibit inactivation of the NF2 tumor suppressor gene, which is lost via copy number variants and/or somatic damaging mutations in 60–80% of cases." (PMID 38730704, 2024).
meningioma (continued). "Subsequently, in adult zebrafish, nf2a/b knockout triggered the development of a spectrum of tumors, including vestibular Schwannomas, spinal Schwannomas, meningiomas and retinal hamartomas, mirroring the tumor manifestations observed in patients with NF-2." (PMID 39415595, 2024). "Among the earliest mutations often detected through FISH analysis are those occurring in the NF2 gene, present in nearly half of all meningioma cases." (PMID 39022728, 2024). "The experimental results showed that, compared to the control group, NF2‐associated meningioma cells exhibited increased expression of EGFR, indicating enrichment of EGFR in NF2‐associated meningioma cells." (PMID 38828669, 2024). "The primary and recurrence TMBs were in the same range as previously reported nonsynonymous TMB estimates for higher-grade, NF2-altered recurrent meningioma tumors." (PMID 39935847, 2024). "These alterations can co-occur with mutations in SMARCB1, which also resides on chromosome 22 near the NF2 gene, with meningiomas typically found near the midline falx." (PMID 38730704, 2024). "Other genetic alterations, exclusive of NF2 that are reported in sporadic adult meningiomas, include TRAF7, SMO, KLF4, AKT1 and PIK3CA." (PMID 39612013, 2024). "NF2-mutant meningiomas and meningiomas with YAP1::MAML2 gene fusions share a gene expression profile, and meningioma in mice generated from YAP::MAML2 expression is phenotypically consistent with activated YAP expression." (PMID 40491864, 2024). "Recurrent 1p-22q-NF2- meningiomas were enriched for a newly identified GSTM1 null genotype compared to primary meningiomas that showed variable GSTM1 expression and independent external validation was performed." (PMID 39726707, 2024). "Aggressive meningiomas can be divided into three groups based on genomic analysis of their NF2 status: NF2 mutant, NF2 agnostic, and NF2 wild-type." (PMID 39202270, 2024). "Alterations in NF2, moesin-ezrin-radixin like (MERLIN) tumor suppressor, are the most common genetic abnormality in meningioma, with up to 60% of sporadic meningiomas harboring them." (PMID 39726707, 2024). "The oncogenic functions of these YAP1 fusions fundamentally rely on their ability to exert deregulated YAP activity, and YAP1 fusion-positive human meningiomas resemble NF2 mutant meningiomas by both gene expression and DNA methylation-based classification." (PMID 38571886, 2024). "A long-term retrospective follow-up (13.5 ± 5.5 years) study involving total 159 meningiomas in 37 patients with NF2 was performed." (PMID 37752594, 2023). "Meningioma location and NF2 also missed statistical significance regarding progression-free survival." (PMID 35838837, 2023). "Here, we provide evidence that NF2-deficient meningiomas express significantly higher levels of widely recognized oncogenes BCL2 and GLI1 compared to meningiomas with missense TRAF7 mutations." (PMID 36937440, 2023). "It is also interesting that the relative expression level of antisense long non-coding RNA (lncRNA) FOXD3-AS1 was also significantly increased in NF2-2 meningiomas compared to NF2-1 tumors." (PMID 36937440, 2023). "Group 2 meningiomas have intermediate prognosis, NF2 inactivation, are free of chromosomal instabilities, and are enriched in immune cells." (PMID 38001599, 2023). "In the meningiomas analysed in NF2 patients, the RNA-seq-derived immune metrics (CIBERSORT, xCell, and ESTIMATE) were strongly correlated with one another (Spearman r = 0.56–0.85, p < 0.001)." (PMID 37752594, 2023). "Unsupervised hierarchical clustering of genes revealed two molecular groups that mostly matched meningiomas in patients with NF2 and sporadic NF2-altered meningiomas." (PMID 37752594, 2023). "This study investigated the clinical, histological, and molecular characteristics of meningiomas in NF2 patients to decipher the mechanisms of clinical difference between meningiomas in NF2 patients and sporadic NF2-altered meningiomas." (PMID 37752594, 2023).
meningioma (continued). "Small series and case reports showed mutations or chromosomal losses of NF2 or SMARCB1 in MM, as well as distinct somatic mutations in samples of different meningiomas of one individual." (PMID 36781550, 2023). "Rarely, NF2 mutant meningiomas are found more midline, in the parafalcine region, and harbor somatic co-mutations in the SWI/SNF transcription factor gene, SMARCB1." (PMID 37010677, 2023). "This patient demonstrates clinical hallmarks of NF2 such as bilateral vestibular schwannomas, ependymomas, and meningiomas." (PMID 38058737, 2023). "both noted that NF2 gene inactivation was less likely to be detected in radiation-induced meningiomas." (PMID 37675219, 2023). "When comparing immune cell infiltration between NF2 patients and sporadic NF2-altered meningiomas, the tumours of NF2 patients showed higher immune infiltration than those observed in sporadic tumours." (PMID 37752594, 2023). "The latest integrated molecular classification of sporadic meningiomas classifies them into four molecular groups (immunogenic, benign NF2 wild-type, hypermetabolic, and proliferative)." (PMID 37752594, 2023). "Few of these biomarkers are being studied in clinical trials to develop targeted personalized therapies, including a phase II trial (NCT02523014) to investigate drugs in AKT1-mutant, SMO-mutant, or NF2-mutant meningiomas." (PMID 38001599, 2023). "On the other hand, NF2 meningiomas expressed high levels of genes for muscle specific carbonic anhydrase CA3 and matrix metalloproteinase MMP13 compared to TRAF7 tumors." (PMID 36937440, 2023). "This is regarded as one of the earliest events in the carcinogenesis process, and meningiomas with NF2 alterations tend to accumulate copy number variations, resulting in a subsequent increase in biological aggressiveness." (PMID 37366279, 2023). "HERV-K expression has been observed in primary cells derived from patient meningiomas with NF2 mutations; further, FDA-approved retroviral protease inhibitors such as ritonavir, atazanavir, and lopinavir reduced the proliferation of grade 1 meningioma cells." (PMID 37173979, 2023). "KEGG gene set enrichment analysis found that meningiomas with NF2 inactivation are enriched for “pathways in cancer”, indicating the susceptibility of NF2 meningiomas to undergo further aggressive evolution." (PMID 36937440, 2023). "The alteration of the tumor suppressor gene NF2 is present in meningiomas arising in NF2 and in 60% of sporadic meningiomas." (PMID 37366279, 2023). "YAP1-MAML2 positive meningiomas have been reported to exhibit similarities to NF2 mutant meningiomas, showing an elevated level of YAP1 signaling and a comparable response to a specific group of pharmaceutical reagents." (PMID 37628996, 2023). "The RNA sequencing confirmed equally low NF2 expression in patients with NF2 and sporadic NF2-altered meningiomas (p = 0.78)." (PMID 37752594, 2023). "Mutations in Nf2, TRAF7, KLF4, AKT1, and SMO are present in approximately 80% of sporadic meningiomas." (PMID 37898750, 2023). "They then classified these same meningiomas based on transcriptomic profile (RNAseq), copy number status, and NF2 status/degree of chromosomal instability, then assessed the degree of agreement between classification using these 4 different platforms." (PMID 36840836, 2023). "This study investigated meningiomas' clinical, histological, and molecular characteristics in NF2 patients." (PMID 37752594, 2023). "Most meningiomas in NF2 patients were stable, and the mean annual growth rate was 1.0 ± 1.8 cm3/year." (PMID 37752594, 2023). "The frequency of WHO grade I meningiomas differed between tumour in NF2 patients and sporadic NF2-altered tumours (p = 0.04)." (PMID 37752594, 2023). "Merlin is known to act as a tumor suppressor by inhibiting cell growth through contact inhibition and activation of multiple signaling pathways, and genetic inactivation of NF2 prevents the production of Merlin, leading to meningioma formation." (PMID 38001599, 2023).
meningioma (continued). "Co-deletion of CHEK2 and NF2 (both on chromosome 22) was reported to contribute to meningioma pathogenesis and genomic instability." (PMID 36980535, 2023). "Aside from chromosome 22q and the NF2 gene, cytogenetic studies have shown meningiomas to be characterized by complex patterns of other chromosomal losses and gains that vary with biological aggressiveness." (PMID 36840836, 2023). "Regarding WHO histological grade, the frequency of WHO grade I meningiomas in NF2 patients’ tumours was 92.1% (80.9% in sporadic NF2-altered meningiomas; p = 0.04)." (PMID 37752594, 2023). "Although NF2 involvement is one of the important findings in meningioma, the frequency and occurrence are restricted to around 40% of total tumors." (PMID 37887327, 2023). "Studies have demonstrated that blocking the interaction between YAP1 and TEAD or targeting TEAD auto-palmitoylation can effectively inhibit tumor formation and suppress tumor growth in the YAP1 fusion/NF2 mutant meningioma and schwannoma." (PMID 37628996, 2023). "Previous reports on meningiomas have shown with RNA sequencing and methylation profiling, that NF2 gene rearrangements were present in 12/31 of radiation-induced meningiomas, an observation previously unreported in sporadic meningioma." (PMID 37051330, 2023). "Of the 189 sporadic NF2-altered meningiomas, 80.9% were WHO grade I (meningothelial: 39.7%, transitional/fibrous: 39.2%, others: 2.1%) and 19.1% were WHO grade II/III." (PMID 37752594, 2023). "We compared the mRNA expression profiles of meningiomas between germline NF2 patients (5 tumours) and mosaic NF2 patients (9 tumours)." (PMID 37752594, 2023). "GO analyses found enrichment of epidermis development and regulation of cell activation pathways in TRAF7 and NF2 meningiomas, respectively." (PMID 36937440, 2023). "For this reason, a recent experimental study (NCT02523014) using GSK2256098, a FAK inhibitor, in patients with NF2 mutant meningiomas, is now under evaluation." (PMID 37760490, 2023). "Further research has shown that the YAP1 fusion NF2 wild-type meningiomas exhibit high YAP1 activity and express a similar gene profile as NF2 mutant meningiomas." (PMID 37628996, 2023). "Our results showed that meningiomas in NF2 patients have high immune activity, as identified by identifying myeloid cell infiltration, especially by macrophages." (PMID 37752594, 2023). "Another genetic study revealed that meningioma progression in mice was facilitated by a cooperation between NF2 and cdkn2ab." (PMID 38001599, 2023). "In fact, up to 60% of sporadic meningiomas have biallelic inactivation of NF2 due to chromosome 22 monosomy combined with NF2 point mutations." (PMID 38001599, 2023). "RAPGEFL1, encoding RAP guanine nucleotide exchange factor like 1 protein, displayed the highest statistical significance of differential expression in TRAF7 meningiomas compared to NF2 counterparts." (PMID 36937440, 2023). "We can see from our analysis of keyword trends that some keywords related to meningioma molecular characteristics are gradually increasing, such as NF2 and AKT1." (PMID 36969005, 2023). "Currently, the multi-arm trial NCT02523014 is evaluating abemaciclib in recurrent meningioma harboring CDK pathway or NF2 alterations." (PMID 36181606, 2023). "Of the 159 meningiomas in NF2 patients, 28 meningiomas (17.6%) in 25 patients (43.1%) were resected during the follow-up period." (PMID 37752594, 2023). "In contrast, meningiomas in NF2 patients predominantly comprise the immunogenic group with macrophage infiltration." (PMID 37752594, 2023). "Meningiomas in the third group had the worst prognosis, displayed NF2 alterations coupled with high chromosomal instability, and were resistant to cytotoxic treatment." (PMID 37296907, 2023). "The loss of several chromosomal regions, including NF2 and CDKN2A, which is associated with aggressive meningiomas, was considered a significant driver event for malignant progression." (PMID 38073632, 2023).